CFTR (CF transmembrane conductance regulator)
Diseases named in the same sentence as CFTR in open-access papers (continued):
Sharing a sentence is not in itself a finding about the gene and the disease.
cystic fibrosis (continued). "Cystic fibrosis is a genetic disease caused by hundreds of different mutations of CFTR, a gene encoding the CFTR protein, a chloride/HCO3− channel of the plasma membrane." (PMID 36077010, 2022). "Cystic fibrosis is the result of a CFTR mutation, which is well described in terms of lung symptoms." (PMID 36277193, 2022). "For the development of therapeutics against cystic fibrosis, different modulators of the mutated chloride ion channel CFTR were developed and approved by the Food and Drug Agency (FDA), such as correctors (Lumicaftor, Elexacaftor) or potentiators (Ivacaftor)." (PMID 35456644, 2022). "Cystic fibrosis is a multisystem autosomal recessive disease caused by mutations that lead to deficient or dysfunctional CF transmembrane conductance regulator (CFTR) proteins." (PMID 35887806, 2022). "Failure in maintaining chloride homeostasis in cells is related to various diseases such as cystic fibrosis, in which a malfunctioning of the cystic fibrosis transmembrane conductance regulator (CFTR) gene causes defective chloride transport." (PMID 35323767, 2022). "A mutation in the cystic fibrosis conductance regulator (CFTR) gene sited on chromosome 7 in humans is the cause of cystic fibrosis." (PMID 35765068, 2022). "Cystic fibrosis is a genetic disease caused by the absence or dysfunction of the cystic fibrosis transmembrane conductance regulator (CFTR) protein." (PMID 36698799, 2022). "Cystic fibrosis is a severe life-limiting disease that results from mutations in the cystic fibrosis transmembrane conductance regulator (CFTR) anion channel." (PMID 36098422, 2022). "We investigated the effects of nesolicaftor on the modulator correction of F508del CFTR using the 16HBE gene edited (16HBEge) human bronchial epithelial cell line with the F508del CFTR mutation engineered by the Cystic Fibrosis Foundation Therapeutics Lab." (PMID 36142862, 2022). "Today, more than 2000 CFTR variants have been identified in patients with Cystic Fibrosis and CFTR-related disorders." (PMID 35650428, 2022). "Cystic fibrosis is caused by different mutations in the CF transmembrane conductance regulator (CFTR) gene." (PMID 35883573, 2022). "Low CFTR mRNA expression due to nonsense-mediated mRNA decay (NMD) is a major hurdle in developing a therapy for cystic fibrosis caused by the W1282X mutation in the CFTR gene." (PMID 35624092, 2022). "Individuals who are heterozygous for a disease-causing mutation in CFTR (CF carriers), typically have normal sweat chloride, and have been considered protected from the manifestations of cystic fibrosis." (PMID 35668512, 2022). "Cystic fibrosis is a hereditary disease caused by a mutation in the cystic fibrosis transmembrane conductance regulator (CFTR) gene." (PMID 34106792, 2022). "Cystic fibrosis is a genetic disease caused by mutations in the cystic fibrosis transmembrane conductance regulator (CFTR) protein, a plasma membrane protein expressed on the apical surface of secretory epithelia of the airways." (PMID 36232697, 2022). "Cystic fibrosis is caused by dysfunction of the CF transmembrane conductance regulator (CFTR), which is a recessive genetic disease with a single gene mutation." (PMID 36325365, 2022). "Cystic fibrosis is an autosomal recessive lethal genetic disorder caused by mutations in the CFTR gene." (PMID 36017299, 2022). "Cystic fibrosis is an inherited disorder caused by biallelic mutations of the CF transmembrane conductance regulator (CFTR) gene." (PMID 35315363, 2022). "The W1282X nonsense mutation in the CFTR gene causes cystic fibrosis by reducing its mRNA and functional protein levels." (PMID 35624092, 2022). "For example, cystic fibrosis is caused by disruption of the epithelial chloride channel cystic fibrosis transmembrane regulator (CFTR)." (PMID 35237593, 2022).
cystic fibrosis (continued). "Cystic fibrosis is a rare genetic disease caused by mutations in the cystic fibrosis transmembrane conductance regulator (CFTR), an epithelial anion channel expressed in several vital organs." (PMID 35327663, 2022). "Cystic fibrosis is caused by biallelic mutations in the Cystic Fibrosis Transmembrane conductance Regulator (CFTR) gene, which translates to the CFTR protein, a transmembrane chloride channel mainly present in the respiratory and gastro-intestinal epithelium." (PMID 35676908, 2022). "Individuals heterozygous for CFTR mutations, who have reduced CFTR activity, are at greater risk for a number of disorders common in cystic fibrosis patients." (PMID 33572894, 2021). "Cystic fibrosis is a genetic disease caused by mutations of the cystic fibrosis transmembrane regulator (CFTR) gene, a protein member of the ATP-binding cassette (ABC) transporter superfamily." (PMID 34440701, 2021). "In the present study, hMRP1-Phe434 corresponds to CFTR-Phe191 and a mutation (p.Phe191Leu) has been detected in a patient with cystic fibrosis." (PMID 34575890, 2021). "Cystic fibrosis is an autosomal recessive genetic disease due to mutations in the cystic fibrosis transmembrane conductance regulator (CFTR) gene." (PMID 34440351, 2021). "Mice deficient for the cystic fibrosis transmembrane conductance regulator (CFTR) gene develop multiple complications, including severe pulmonary disease." (PMID 34239729, 2021). "Cystic fibrosis is a severe autosomal recessive disease caused by variants in the cystic fibrosis transmembrane conductance regulator (CFTR) gene, which encodes a chloride ion channel." (PMID 34943888, 2021). "Cystic fibrosis arises from mutations in the CF transmembrane conductance regulator (CFTR) gene, which is responsible for anion transport across CF airway epithelial cells." (PMID 34362100, 2021). "Cystic fibrosis occurs as a result of mutations in the cystic fibrosis transmembrane conductance regulator (CFTR) gene, which lead to misfolding, trafficking defects, and impaired function of the CFTR protein." (PMID 34404863, 2021). "Small compounds able to correct the specific defect induced by mutations are warranted, as it occurred for the pharmacological treatment of CFTR mutations in cystic fibrosis." (PMID 34208776, 2021). "Cystic fibrosis is caused by mutations in the cystic fibrosis transmembrane conductance regulator (CFTR) gene, located on chromosome 7 (7q31.2)." (PMID 33833927, 2021). "Cystic fibrosis is a life-limiting inheritable disease caused by a defect in the cystic fibrosis transmembrane conductance regulator (CFTR) protein, which ultimately impairs mucus hydration, mucociliary clearance, and microbial defense." (PMID 34572234, 2021). "Cystic fibrosis is a fatal autosomal-recessive disease caused by mutations in the gene encoding the cystic fibrosis transmembrane conductance regulator (CFTR) chloride ion channel, resulting in dysfunctional salt and water transport across the epithelia." (PMID 34271850, 2021). "For instance, carrier screening for cystic fibrosis involves the testing of 23 CFTR variants, according to recommendations by the American College of Obstetricians and Gynecologists (ACOG) and the American College of Medical Geneticists (ACMG)." (PMID 34078906, 2021). "Lumacaftor is a treatment for cystic fibrosis by aiding the conformational stability of the F508-del mutated cystic fibrosis transmembrane conductance regulator (CFTR)." (PMID 33785634, 2021). "Subsequently, we sequenced the entire ABCC4 gene and its close relative, the cystic fibrosis associated CFTR gene, a strong AP candidate gene, in 48 cases and 47 controls." (PMID 34768335, 2021). "Cystic fibrosis is an autosomal recessive disease caused by a mutation in the gene coding for the cystic fibrosis transmembrane conductance regulator (CFTR) protein." (PMID 34441045, 2021).
cystic fibrosis (continued). "Sixteen monozygotic cystic fibrosis twin pairs of whom 14 pairs were homozygous for the most common p.Phe508del CFTR mutation were selected from the European Cystic Fibrosis Twin and Sibling Study Cohort." (PMID 33708199, 2021). "A similar finding was noted in the ivacaftor treatment of mutant CFTR associated with cystic fibrosis where the amount of therapeutic effect correlated with the degree of disruption in CFTR protein processing and/or channel function." (PMID 33200471, 2021). "These included the chloride channel that is most frequently mutated in patients with cystic fibrosis (CFTR) and the negative regulator of Wnt signaling TCF7." (PMID 33892786, 2021). "Cystic fibrosis patients are prone to infection since absence of CFTR protein causes demethylation of DNA at the specific CpG sites which overlaps a minimal region to maintain activity of TLR2 promoter." (PMID 33879218, 2021). "Cystic fibrosis is a rare genetic disease, caused by mutations in the cystic fibrosis transmembrane conductance regulator (CFTR) gene which functions as an anion channel across the cell membrane." (PMID 33900491, 2021). "MRT5005 (Translate Bio) is being developed to treat cystic fibrosis, an inherited disease caused by a mutation in the cystic fibrosis transmembrane conductance regulator (CFTR), a chloride channel." (PMID 33816449, 2021). "In cystic fibrosis two classes of mutations affect the expression of CFTR in epithelial cells, resulting in reduced chloride and bicarbonate fluxes across the plasma membrane." (PMID 34572605, 2021). "In humans, three sHSPs (HSPB1/HSP27, HSPB4 and HSPB5) were shown to affect the CFTR (cystic fibrosis transmembrane conductance regulator) protein, whose mutations are the main cause of cystic fibrosis." (PMID 34360841, 2021). "Cystic fibrosis is a genetic disease caused by mutations that impair the function of the CFTR chloride channel." (PMID 33652850, 2021). "Since the discovery of the cystic fibrosis gene, encoding the CF transmembrane regulator (CFTR) protein in 1989, more than 2000 mutations have been reported." (PMID 34017807, 2021). "Cystic fibrosis is an inherited disorder caused by mutations in the gene encoding for the cystic fibrosis transmembrane conductance regulator (CFTR) protein, an ATP-gated chloride channel expressed on the apical surface of airway epithelial cells." (PMID 33669352, 2021). "Patients with cystic fibrosis who have the CFTR loss of function mutation have an increased incidence of dry eye syndrome." (PMID 33921231, 2021). "If the partner carries a CFTR mutation, the couple has up to a 50% risk of having a child with cystic fibrosis or CBAVD, depending on the parents’ type of mutation." (PMID 34300309, 2021). "Cystic fibrosis is a multi-organ hereditary disease caused by a mutation in the gene coding for cystic fibrosis transmembrane conductance regulator (CFTR) protein." (PMID 33920274, 2021). "Cystic fibrosis is an autosomal recessive disease due to mutations of CF transmembrane conductance regulator (CFTR) gene on chromosome 7, which encodes an ion channel." (PMID 34248852, 2021). "For our experiments, we took advantage of the availability of the 16HBE14o- bronchial epithelial cells, provided by the Cystic Fibrosis Foundation, whose CFTR gene locus has been edited to introduce various CF-causing PTCs." (PMID 34769402, 2021). "Cystic fibrosis is an autosomal recessive disease caused by genetic variants of the cystic fibrosis transmembrane conductance regulator (CFTR) gene." (PMID 34276759, 2021). "Cystic fibrosis is a commonly lethal hereditary syndrome that affects the lung and digestive tract and is triggered by mutations of cystic fibrosis transmembrane conductance regulator (CFTR) gene, situated on chromosome 7." (PMID 34977000, 2021). "The genetic mechanism underlying cystic fibrosis is linked to a combination of genetic mutations in the gene coding for the cystic fibrosis transmembrane conductance regulator (CFTR)." (PMID 34207804, 2021).
cystic fibrosis (continued). "Cystic fibrosis is the most prevalent inherited disease caused by a defect in the cystic fibrosis transmembrane conductance regulator (CFTR) gene." (PMID 34213646, 2021). "Cystic fibrosis is a genetic disorder caused by a mutation in the CF transmembrane conductance regulator (CFTR) gene." (PMID 33572846, 2021). "The genetic disease cystic fibrosis is caused by mutations in the epithelial anion channel cystic fibrosis transmembrane conductance regulator (CFTR)." (PMID 34020896, 2021). "CFTR is essential in the regulation of ion and fluid transport in epithelia and its dysfunction causes cystic fibrosis." (PMID 34445719, 2021). "Mutations in CFTR, which impair its expression and function, cause cystic fibrosis, the most common lethal genetic disease, and CF patients showed that they exhibit ocular surface abnormality of low tear film stability." (PMID 33921231, 2021). "For example, cystic fibrosis causing nonsense mutations can reduce the steady‐state levels of CFTR transcripts to 10%–20% of WT." (PMID 33567469, 2021). "In general, compound heterozygous state for two severe mutations leads to cystic fibrosis, while when at least one allele harbors the mild CFTR allele, the CFTR-related disorder occurs." (PMID 34065437, 2021). "Cystic fibrosis is caused by different mutations related to the cystic fibrosis transmembrane regulator protein (CFTR), with F508del being the most common." (PMID 34959696, 2021). "Most cystic fibrosis patients have at least one copy of the F508del CFTR mutation, which results in a protein retained in the endoplasmic reticulum and degraded by the proteosomal pathway." (PMID 34831482, 2021). "In patients with cystic fibrosis, an sSNV in CFTR was linked to decreased expression, and an mRNA-secondary-structure–altering silent codon change contributed to CFTR dysfunction by altering the dynamics of translation, leading to protein misfolding." (PMID 33822938, 2021). "Cystic Fibrosis is an autosomal recessive disease caused by mutations in the gene encoding the cystic fibrosis transmembrane conductance regulator (CFTR)." (PMID 33807548, 2021). "One disease in which in vivo editing would likely be necessary is cystic fibrosis, which is caused by mutations in the cystic fibrosis transmembrane conductance regulator (CFTR) gene." (PMID 34539755, 2021). "Cystic fibrosis is a hereditary disease caused by mutations in the CF transmembrane conductance regulator (CFTR) gene, triggering dysfunction of the anion channel in several organs including the lung and gut." (PMID 34207804, 2021). "The phenotypic variability in cystic fibrosis, the diversity of CFTR variants, and the life-changing promise of modulator therapy make cystic fibrosis a perfect disease for the application of personalized medicine." (PMID 33923202, 2021). "Mutations in the gene encoding the CFTR protein leads to cystic fibrosis, which affects at least 100,000 people worldwide." (PMID 34832033, 2021). "Cystic fibrosis is caused by variants of the cystic fibrosis trans-membrane conductance regulator (CFTR) gene." (PMID 34276759, 2021). "Cystic fibrosis is a progressive genetic disease caused by the presence of mutations in the cftr gene, encoding for a protein called cystic fibrosis transmembrane conductance regulator (CFTR)." (PMID 34438994, 2021). "Cystic fibrosis is caused by a defect in the cystic fibrosis transmembrane conductance regulator protein (CFTR) which instigates a myriad of respiratory complications including increased vulnerability to lung infections and lung inflammation." (PMID 34299226, 2021). "Cystic fibrosis is a monogenic, autosomal, recessive disease characterized by an alteration of chloride transport caused by mutations in the CFTR (Cystic Fibrosis Transmembrane Conductance Regulator) gene." (PMID 33805605, 2021).
cystic fibrosis (continued). "The survival rates of individuals with cystic fibrosis have significantly increased as a result of improved therapies, such as the inclusion of cystic fibrosis transmembrane conductance regulator (CFTR) modulators for some mutations." (PMID 33436426, 2021). "For example, ABCA3 is involved in the formation of a surfactant, and mutations of the ABCC7 gene (also known as cystic fibrosis transmembrane conductance regulator (CFTR)) are the cause of cystic fibrosis." (PMID 34564491, 2021). "Defects in CFTR are known to cause cystic fibrosis, resulting in lung disease, pancreatic insufficiency, and other lethal diseases." (PMID 34910516, 2021). "As CFTR is the gene mutated in cystic fibrosis, cell-specific therapies for this disease can now be evaluated." (PMID 33599610, 2021). "The CFTR has a critical role in transepithelial ion and fluid secretion and homeostasis, and mutations in this gene have been implied in the pathogenesis of cystic fibrosis (CF; Li and Naren, 2005)." (PMID 34211404, 2021). "Cystic fibrosis is an autosomal recessive genetic disease caused by mutations of the cystic fibrosis transmembrane conductance regulator (CFTR) gene." (PMID 33807165, 2021). "Cystic fibrosis is an inherited disease with mutations on the cystic fibrosis transmembrane conductance regulator (CFTR) gene." (PMID 33467433, 2021). "Cystic fibrosis is a life-shortening disease that is caused by mutations in the CF transmembrane conductance regulator (CFTR) gene that lead to the loss or dysfunction of CFTR channel activity." (PMID 33567498, 2021). "Kalydeco® (ivacaftor), Orkambi® (lumacaftor/ivacaftor) and Symkevi® (tezacaftor/ivacaftor) were the first treatments authorized in the European Union to target the underlying mechanism of the dysfunctional CFTR protein in cystic fibrosis." (PMID 34858177, 2021). "Cystic Fibrosis is an autosomal recessive disease caused by mutations in the gene encoding cystic fibrosis transmembrane conductance regulator (CFTR), a chloride ion channel." (PMID 34868211, 2021). "In cystic fibrosis, the loss of the CF transmembrane conductance regulator (CFTR) has devastating consequences for ASL homeostasis." (PMID 33810137, 2021). "Cystic fibrosis is one of the most common genetic diseases in western populations (approximately 1 in 4000 newborns) and is caused by mutations in the CFTR gene." (PMID 33959146, 2021). "Cystic fibrosis is caused by mutations in the gene encoding cystic fibrosis transmembrane conductance regulator (CFTR), a member of the ATP-binding cassette (ABC) Transporter Superfamily, but the sole member that functions as a chloride channel." (PMID 34163370, 2021). "Cystic fibrosis is a genetic disorder caused by mutations in the gene that encodes the CF transmembrane conductance regulator (CFTR) protein, which plays an important role as a bicarbonate and chloride channel at the surface of epithelial cells." (PMID 33659247, 2021). "Cystic fibrosis is a common, life-shortening, recessive genetic disorder, resulting from mutations in the cystic fibrosis transmembrane conductance regulator (CFTR) gene." (PMID 34084147, 2021). "Cystic fibrosis is a life-limiting genetic disorder caused by loss-of-function mutations in the gene which codes for the CF transmembrane conductance regulator (CFTR) Cl− channel." (PMID 33810137, 2021). "Nearly 70,000 individuals worldwide suffer from cystic fibrosis, a systemic genetic disorder induced by mutations in the Cystic Fibrosis Transmembrane Conductance Regulator (CFTR) gene." (PMID 34072374, 2021). "Cystic fibrosis is a disease caused by mutations in the cystic fibrosis transmembrane conductance regulator (CFTR) protein, and it is the most widespread recessively inherited disorder in North America and Europe." (PMID 34064516, 2021).